AKAP8 (A-kinase anchoring protein 8)
Description:
Anchoring protein that mediates the subcellular compartmentation of cAMP-dependent protein kinase (PKA type II). Acts as an anchor for a PKA-signaling complex onto mitotic chromosomes, which is required for maintenance of chromosomes in a condensed form throughout mitosis. Recruits condensin complex subunit NCAPD2 to chromosomes required for chromatin condensation; the function appears to be independent from PKA-anchoring. May help to deliver cyclin D/E to CDK4 to facilitate cell cycle progression. Required for cell cycle G2/M transition and histone deacetylation during mitosis. In mitotic cells recruits HDAC3 to the vicinity of chromatin leading to deacetylation and subsequent phosphorylation at 'Ser-10' of histone H3; in this function may act redundantly with AKAP8L. Involved in nuclear retention of RPS6KA1 upon ERK activation thus inducing cell proliferation. May be involved in regulation of DNA replication by acting as scaffold for MCM2. Enhances HMT activity of the KMT2 family MLL4/WBP7 complex and is involved in transcriptional regulation. In a teratocarcinoma cell line is involved in retinoic acid-mediated induction of developmental genes implicating H3 'Lys-4' methylation. May be involved in recruitment of active CASP3 to the nucleus in apoptotic cells. May act as a carrier protein of GJA1 for its transport to the nucleus. May play a repressive role in the regulation of rDNA transcription. Preferentially binds GC-rich DNA in vitro. In cells, associates with ribosomal RNA (rRNA) chromatin, preferentially with rRNA promoter and transcribed regions. Involved in modulation of Toll-like receptor signaling. Required for the cAMP-dependent suppression of TNF in early stages of LPS-induced macrophage activation; the function probably implicates targeting of PKA to NFKB1 (By similarity).
Synonyms: AKAP-8; AKAP 95; AKAP95; DKFZp586B1222; AKAP-95
Tractability: PROTAC: UniProt records ubiquitination sites on it; ubiquitination databases record sites on it; its protein half-life has been measured.
Gene: Protein-coding gene on chromosome 19 (15,353,385 to 15,379,829, reverse strand). Ensembl gene ENSG00000105127.
Subcellular location: Nucleus; Nucleus matrix; Nucleus, nucleolus; Cytoplasm
Subcellular location (Human Protein Atlas): Nucleoplasm
Gene Ontology:
Molecular function: histone deacetylase binding; protein binding; protein kinase A regulatory subunit binding; RNA binding; DNA binding; double-stranded DNA binding; NF-kappaB binding; zinc ion binding
Biological process: cell cycle G2/M phase transition; mitotic cell cycle; mitotic chromosome condensation; signal transduction; cellular response to lipopolysaccharide; cellular response to prostaglandin E stimulus; negative regulation of tumor necrosis factor production
Cellular component: membrane; nuclear matrix; nucleolus; nucleoplasm; nucleus; condensed chromosome; cytoplasm; female pronucleus
Genetic constraint (gnomAD): Loss-of-function variants: 24 observed, 70.36 expected, observed/expected ratio (o/e) 0.34, 90% interval 0.25 to 0.48. The upper end of that interval is the gene's LOEUF score, 0.48, which puts it in group 2 of 6, group 1 being the genes least tolerant of losing a copy. Missense variants: 971 observed, 974.45 expected, observed/expected ratio (o/e) 1, 90% interval 0.94 to 1.05. Synonymous variants: 400 observed, 375.39 expected, observed/expected ratio (o/e) 1.07, 90% interval 0.98 to 1.16.
Homologues: Orthologues: chimpanzee AKAP8 (99% identical), macaque AKAP8 (96% identical), dog AKAP8 (82% identical), rat Akap8 (80% identical), mouse Akap8 (79% identical), guinea pig AKAP8 (79% identical), pig AKAP8 (78% identical), rabbit AKAP8 (75% identical). Paralogues in human: AKAP8L (32% identical), ZNF326 (24% identical).
Diseases named in the same sentence as AKAP8 in open-access papers:
AKAP8 is named in the same sentence as 22 diseases in open-access papers, as found by Europe PMC text mining. Sharing a sentence is not in itself a finding about the gene and the disease. The quoted sentences say what the papers report.
breast carcinoma (7 papers, 2015 to 2024). "Taken together, these gain-and-loss of function analyses of AKAP8 demonstrate that AKAP8 prevents breast cancer metastasis to the lung." (PMID 31980632, 2020). "On the other hand, the resistance of A-kinase anchoring protein 8 (AKAP8) to EMT can inhibit breast cancer metastasis." (PMID 36090904, 2022). "Functionally, we used both a PDX model of tumor metastasis and a highly metastatic cell line LM2 and showed that AKAP8 knockdown promotes breast cancer lung metastasis and ectopic expression of AKAP8 inhibits metastasis." (PMID 31980632, 2020). "Further analysis of the METABRIC breast cancer data set showed that AKAP8 expression positively correlates with overall survival, most significantly in Luminal A, Luminal B, and HER2 + subtypes." (PMID 31980632, 2020). "Indeed, as demonstrated, cells with loss of AKAP8 exhibit accelerated EMT and elevated breast cancer metastatic potential." (PMID 35954483, 2022). "Cells with loss of AKAP8 show accelerated EMT and enhanced breast cancer metastatic potential." (PMID 31980632, 2020). "High levels of AKAP8 expression predicts a better survival of breast cancer patients." (PMID 31980632, 2020). "As EMT is essential for tumor metastasis, our finding that AKAP8 inhibits EMT prompted us to determine whether AKAP8 inhibits breast cancer metastasis." (PMID 31980632, 2020). "It has been shown that AKAP8 can inhibit the activity of the splicing factor and EMT-promoter heterogeneous nuclear ribonucleoprotein M (hnRNPM), thus inhibiting EMT and breast cancer metastasis in murine models." (PMID 39682684, 2024). "Furthermore, as the CLSTN1 splice isoform levels, but not its transcription level, correlates with patient survival, we speculate that tipping the AKAP8 downstream target from CLSTN1-L to CLSTN1-S may be an effective strategy for the treatment of breast cancer." (PMID 31980632, 2020). "In conclusion, this work has led to the identification of a new role of the RNA-binding protein AKAP8 in suppressing EMT and breast cancer metastasis." (PMID 31980632, 2020). "In this study, we report the identification of the A kinase anchoring protein 8 (AKAP8) as an RNA-binding protein that inhibits EMT and breast cancer metastasis through the regulation of alternative splicing." (PMID 31980632, 2020). "We demonstrated that the CLSTN1-S splice isoform, generated by AKAP8-mediated alternative splicing, inhibits EMT and shows an inverse correlation with breast cancer progression." (PMID 31980632, 2020). "Here we report the identification of A-Kinase Anchor Protein (AKAP8) as a splicing regulatory factor that impedes EMT and breast cancer metastasis." (PMID 31980632, 2020). "Considering the oncogenic role of DDX5 in breast cancer, the overexpression of DDX5 could be crucial for limiting the oncosuppressive action of AKAP8 through its nuclear sequestration." (PMID 35954483, 2022). "Moreover, AKAP8 expression and the alternative splicing of CLSTN1 predict breast cancer patient survival." (PMID 31980632, 2020). "As a complementary approach, we ectopically expressed AKAP8 in a lung metastatic breast cancer cell line LM2, a derivative of MDA-MB-231 cells, and examined whether forced expression of AKAP8 inhibits lung metastasis." (PMID 31980632, 2020). "Functionally, AKAP8 inhibits EMT and breast cancer metastasis to the lung." (PMID 31980632, 2020).
autism (2 papers, 2015 to 2018). Persistent deficits in social interaction and communication and interaction as well as a markedly restricted repertoire of activity and interest as well as repetitive patterns of behavior. "We present here a patient with autism and ID with an inherited duplication at 19p13.12 and discuss the relationship between altered gene dosage at this locus, involving AKAP8 and/or AKAP8L in particular, and each of head size and autism." (PMID 26076356, 2015). "Towards determination of which of AKAP8 and AKAP8L may be involved in the modulation of head size and risk for disease, we analyzed exome sequencing data for 693 autism families (2591 individuals) where head circumference data were available." (PMID 26076356, 2015). "Taken together, findings support the idea that gene dosage at 19p13.12, and AKAP8 and/or AKAP8L in particular, play an important role in modulation of head size and may contribute to autism risk." (PMID 26076356, 2015). "Data support A kinase anchor protein 8 and 8-like (AKAP8 and AKAP8L) as candidate genes involved in regulation of head growth, an interesting finding given previous work implicating the AKAP gene family in autism." (PMID 26076356, 2015).
lung carcinoma (2 papers, 2016 to 2023). "TSA is an anticancer drug that inhibits the growth of lung cancer cells through histone hyperacetylation, and AKAP8 is involved in DNA replication and condensation during the cell cycle." (PMID 37072452, 2023).
colorectal cancer (1 paper, 2022). A primary or metastatic malignant neoplasm that affects the colon or rectum. "The RNA-binding protein AKAP8 (A-Kinase Anchoring Protein 8), also known as AKAP95, is overexpressed in ovarian and colorectal cancers and is required to inhibit oncogene-induced senescence." (PMID 35406602, 2022).
mastitis (1 paper, 2021). Inflammation of breast tissue during lactation or postpartum due to an obstructed duct or infection. "Furthermore, previously known mastitis related genes such as LUZP2, AKAP8 and MEGF10 were also identified in our study as candidate genes for SCS in the RB breed." (PMID 34680890, 2021).
renal cell carcinoma (1 paper, 2018). "Interestingly, in line with the findings in our study, somatic mutations in AKAP8 and AKAP9 were found in multiple metastases in a patient with renal cell carcinoma but were both absent in the primary tumor." (PMID 29433456, 2018).
small cell lung carcinoma (1 paper, 2023). Small cell lung cancer (SCLC) is a highly aggressive malignant neoplasm, accounting for 10-15% of lung cancer cases, characterized byrapid growth, and early metastasis. "AKAP8 and ADRB2 showed specific effects in both TSA- and small-cell lung cancer (SCLC) cell lines, NCIH1694." (PMID 37072452, 2023).
viral infections (1 paper, 2024). "Specifically, STIP1, PGAM5, and AKAP8 were over-expressed in VM samples and associated with viral infections." (PMID 38902725, 2024).
cancer (15 papers, 2016 to 2024). A tumor composed of atypical neoplastic, often pleomorphic cells that invade other tissues. "In addition, AKAP8 is upregulated in many types of cancer, including ovarian, lung, and esophageal squamous carcinoma, and mediates cell-cycle regulation and mitotic DNA condensation." (PMID 35189899, 2022). "AKAP8 plays an important role in tumorigenesis by supporting cancer cell growth." (PMID 36522343, 2022). "Another novel p16 interactor identified here, AKAP8, dynamically interacts with other proteins during cell cycle progression and appears to play an important role in promoting lung, ovarian and rectal cancers." (PMID 32204550, 2020). "However, another research team revealed that AKAP8 may promote tumorigenesis through the formation of phase-separated and liquid-like condensates in the cancer cell nucleus and regulating alternative splicing." (PMID 35189899, 2022). "AKAP8L, the homolog of the scaffold protein AKAP8, links M protein cluster to E and N members in the PPI network, influencing cancer cell tumorigenesis and metastasis." (PMID 36528612, 2022). "The identification of AKAP8 in suppressing EMT and cancer metastasis was through a biochemical approach to capture proteins that interact with hnRNPM, previously shown to promote EMT and tumor metastasis by regulating alternative splicing of CD44." (PMID 31980632, 2020).
tumor (8 papers, 2016 to 2024). "Having established the function of AKAP8 in inhibiting tumor metastasis, we next sought to determine its underlying mechanisms." (PMID 31980632, 2020). "The reduced expression of genes involved in stabilization of adherence proteins (AKAP5, 9, 11 and 12) as well as increase expression of genes associated with poor prognosis and proliferation (AKAP3 and AKAP8) strongly underscores the involvement of AKAP genes during tumor growth and dissemination." (PMID 29433456, 2018). "AKAP8 (A-kinase anchor protein 8), also known as AKAP95, is an RNA-binding protein and a splicing regulatory factor that acts as a tumor suppressor protein by interacting with hnRNPM, antagonizing its splicing activity on CD44 exon skipping." (PMID 35954483, 2022). "To capture the effect of AKAP8 on tumor metastasis, we inoculated NSG mice with 1 × 105 control or AKAP8 knockdown cells through tail vein injection and measured the potential of lung metastasis." (PMID 31980632, 2020). "Our study provides a functional role for AKAP8 in RNA metabolism and connected it further to a tumor metastasis suppression phenotype." (PMID 31980632, 2020). "AKAP8 knockdown with two different shRNAs significantly increased BLI signals compared with control, indicating the enhanced ability of metastatic tumor formation in mice in response to AKAP8 depletion." (PMID 31980632, 2020). "The protein sequence of AKAP8L exhibits a similarity of up to 61% with that of AKAP8, suggesting that AKAP8L and AKAP8 may have similar functions in tumor genesis and metastasis." (PMID 37683130, 2023). "The positive correlation of AKAP8 expression and metastasis-free survival is congruent with our experimental findings that AKAP8 promotes CD44v8 inclusion and inhibits CD44s production, the isoform that promotes EMT and tumor metastasis." (PMID 31980632, 2020). "Moreover, we demonstrated that cytoplasmic p16 interacted with CDK4 and other unreported proteins, such as BANF1, AKAP8 and AGTRAP, which could sequester p16 to avoid nuclear translocation, and then, impair its anti-tumor function." (PMID 32204550, 2020).
AKAP8 also shares sentences with these, for which no sentence is quoted: colon carcinoma (2 papers); rectal cancer (2); bacterial infection (1); esophageal cancer (1); gastric adenocarcinoma (1); Huntington disease (1); lymph node metastasis (1); metastatic tumors (1); microcephaly (1); prostate carcinoma (1); sex development disorders (1); T-cell leukemia (1).